RN7SL261P (RNA, 7SL, cytoplasmic 261, pseudogene)
Gene: Miscellaneous RNA gene on chromosome 1 (147,689,256 to 147,689,537, forward strand). Ensembl gene ENSG00000277762.
Homologues: Orthologues: chimpanzee Metazoa_SRP (99% identical), macaque Metazoa_SRP (87% identical). Paralogues in human: RN7SL1 (83% identical), RN7SL2 (82% identical), RN7SL3 (81% identical), RN7SL448P (81% identical), RN7SL230P (80% identical), RN7SL566P (80% identical), RN7SL788P (80% identical), RN7SL126P (80% identical), RN7SL357P (79% identical), RN7SL45P (79% identical), RN7SL14P (79% identical), RN7SL498P (79% identical), and 705 more.